MAPK14 (mitogen-activated protein kinase 14)
Diseases named in the same sentence as MAPK14 in open-access papers (continued):
Sharing a sentence is not in itself a finding about the gene and the disease.
osteoporosis (6 papers, 2020 to 2024). A condition of reduced bone mass, with decreased cortical thickness and a decrease in the number and size of the trabeculae of cancellous bone (but normal chemical composition), resulting in increased fracture incidence. "After screening the core therapeutic ingredients, a PPI network was constructed to determine core targets; our results showed that AKT1, CASP3, EGFR, ESR1, IGF1, MAPK1, and MAPK14 are important for AB–DA treatment of osteoporosis." (PMID 37849727, 2023). "Furthermore, 36 hub genes of XLGB, such as EGF, EGFR, MTOR, MAPK14 and NFKB1, were considered potential therapeutic targets, suggesting the underlying mechanisms of XLGB acting on osteoporosis." (PMID 32620113, 2020). "Our study revealed 72 targets between DHT and osteoporosis, including CTSK, MMP13, MAPK14, CASP3, etc., suggesting that these targets are principally related to the inflammatory response, apoptosis, and oxidative stress, which is consistent with the results of GO and KEGG analyses." (PMID 36210855, 2022). "Moreover, anhydroicaritin may have an adverse effect on MAPK14, which further inhibits the PI3K-Akt signaling pathway and ultimately alleviates osteoporosis symptoms." (PMID 32620113, 2020).
Stroke (6 papers, 2011 to 2025). Sudden impairment of blood flow to a part of the brain due to occlusion or rupture of an artery to the brain. "Our results showed that ECH1, MAPK14, and BRD2 were significantly correlated with stroke, and no pleiotropy or heterogeneity was detected (P < 0.05)." (PMID 40918984, 2025).
cervical carcinoma (5 papers, 2014 to 2025). A carcinoma arising from either the exocervical squamous epithelium or the endocervical glandular epithelium. "For instance, the increase of TRIB3 expression in HeLa cervical carcinoma cells resulted in the inhibition of MAPK14, MAPK3/1 and MAPK8 (JNK) activities via binding to MAPK kinase." (PMID 24834131, 2014). "Furthermore, knock down of MAPK1 or MAPK14 with two respective specific siRNAs did not significantly affect IL‐17‐induced resistance toward chemoradiotherapy in three tested cervical cancer cells." (PMID 34469022, 2021).
clear cell renal cell carcinoma (5 papers, 2020 to 2025). "Interestingly, MAPK14 was also found to decrease progressively at higher grades of renal clear cell carcinoma." (PMID 37509437, 2023). "We examined the expression of mitogen‐activated protein kinase 14 (MAPK14) and cell division cycle 25B (CDC25B) in clear cell renal cell carcinoma (ccRCC) and healthy tissue using the cancer genome atlas database and clinical samples." (PMID 31856414, 2020).
diabetic foot ulcers (5 papers, 2017 to 2025). "In a study that enrolled 699 patients with T1DM/T2DM+DN and diabetic foot ulcers and 2695 controls (patients with T1DM/T2DM+DN, but without foot ulcers), the single-nucleotide polymorphism rs80028505 (Chr6p2131) in MAPK14 reached genome-wide significance." (PMID 39997711, 2025).
pancreatic cancer (5 papers, 2007 to 2024).
renal cell carcinoma (5 papers, 2010 to 2022). "As a result, five aging-related genes (DUSP22, MAPK14, MAPKAPK3, STAT1, and VCP) in normal tissues were found to be significantly associated with a worse survival outcome in patients with renal cell carcinoma (RCC)." (PMID 34207247, 2021).
schizophrenia (5 papers, 2008 to 2018). A major psychotic disorder characterized by abnormalities in the perception or expression of reality. "Although, the minor allele frequencies of these SNPs are low their odds ratios point in the same direction and suggest that variants of MAPK14 could provide protection against schizophrenia." (PMID 18460190, 2008). "As we cannot draw firm conclusions with the current data further investigations with testing of more loci are required to clarify whether ENO2, FBP1, MAPK14 and PCK1 variants provide genetic support for the view that alterations in glucose metabolism are intrinsic to schizophrenia etiology." (PMID 18460190, 2008). "Last, we investigated the mRNA expression levels of MAPK14, GFAP and the inflammation markers, IL1B and IL6 in postmortem brain tissues from schizophrenia patients." (PMID 27801899, 2016).
autoimmune disease (4 papers, 2013 to 2023). A disorder resulting from loss of function or tissue destruction of an organ or multiple organs, arising from humoral or cellular immune responses of the individual to their own tissue constituents. "Four DEGs (SOD2, GATA3, PPARG, and MAPK14) were related to various functional categories, including “inflammatory response”, “cell activation”, “autoimmune disease”, and “vascular endothelial cell”." (PMID 34026343, 2021).
colitis (4 papers, 2016 to 2025). Inflammation of the colon. "Our findings showed significant upregulation in mRNA expression of Mapk14 in experimental colitis group." (PMID 33061833, 2020).
fatty liver (4 papers, 2017 to 2025). "(2020) reported that hepatocyte-specific deletion of Mapk14 in HFD-induced fatty liver exacerbated steatosis and liver injury, indicating Mapk14 plays distinct roles in NAFLD." (PMID 36124995, 2022). "We showed that SB203580 treatment or MAPK14 knockdown effectively reduced the phosphorylation of p38α MAPK and promoted the PA-mediated hepatic steatosis, as analyzed by neutral lipid stained liver cells and direct measurement of hepatic TG and PL." (PMID 29022907, 2017). "However, mice fed a high-fat diet (HFD) only develop a fatty liver without progression to NASH, in which the disparity of p38α (also known as mitogen-activated protein kinase 14 (MAPK14)) activation is an important determinant." (PMID 33159158, 2021).
Hepatic fibrosis (4 papers, 2017 to 2023). The presence of excessive fibrous connective tissue in the liver. "Total of 192 potential targets were obtained from 108 active ingredients after removing the redundancy, including MDM2, TNFBR1, MAPK14, and SRC, involved in inflammation, hepatic lipid metabolism, and the development of hepatic fibrosis." (PMID 31354851, 2019). "Some evidences have also reported that mitogen-activated protein kinase 14 (p38 MAPK) signaling is involved in the ROS production and liver fibrosis." (PMID 28423499, 2017). "However, Mapk14 deletion failed to comprehensively reverse hepatic fibrosis." (PMID 37895168, 2023).
kidney cancer (4 papers, 2010 to 2023). Primary or metastatic malignant neoplasm involving the kidney. "We found that five aging-related genes (DUSP22, MAPK14, MAPKAPK3, STAT1, and VCP) from kidney cancer patients were significantly related to patient survival." (PMID 34207247, 2021).
oral cancer (4 papers, 2023 to 2024). "The most common genes involved in the top 10 pathways were MAPK1, MAPK8, MAPK14, and IL6 which were seen to be associated with the MAPK signaling pathway which may be the key pathway through which andrographolide may aid in treating oral cancer." (PMID 39229580, 2024). "This gene codes for the MAPK14 enzyme, which has been identified as a possible regulator of inflammation and is a key component of the tumor microenvironment, as chronic inflammation contributes to the development, progression, and regional metastasis of oral carcinomas." (PMID 37509437, 2023). "The predominant genes implicated in the ten principal pathways were MAPK1, MAPK8, MAPK14, and IL6, which were observed to be linked to the MAPK signaling pathway, perhaps serving as the critical channel through which Galangin may facilitate the treatment of oral cancer." (PMID 39702881, 2024).
acute myeloid leukemia (3 papers, 2019 to 2025). Acute myeloid leukemia (AML) is a group of neoplasms arising from precursor cells committed to the myeloid cell-line differentiation. "Weuse losmapimod, a potent MAPK14 ATP competitive inhibitor, to providea known true positive hit in acute myeloid leukemia (AML) cells." (PMID 37439223, 2023).
aneurysm (3 papers, 2016 to 2026). Bulging or ballooning in an area of an artery secondary to arterial wall weakening. "In summary, through the integration of single-nucleus multi-omics, SRF ChIP-seq, and rigorous wet lab validation, we comprehensively delineated the major transcriptional effectors regulated by MAPK14, a key upstream signaling molecule that facilitates VSMC degeneration and aneurysm formation." (PMID 41526342, 2026).
breast tumor (3 papers, 2018 to 2023). "For instance, the observed enhanced MAPK14 phosphorylation in Wip1-knockout mice has been associated with lower breast tumor formation." (PMID 32433496, 2020).
endometriosis (3 papers, 2019 to 2021). The growth of functional endometrial tissue in anatomic sites outside the uterine body. "Compared with the control group, some genes known to promote the development of endometriosis were decreased in the si-hsa_circ_0063526 agomir group, including MAPK-14, K-ras, N-cadherin, Vimentin, ER-α, ER-β (P < 0.05)." (PMID 34967761, 2021). "The expression of MAPK14 has been found in patients with endometriosis and polycystic ovary syndrome." (PMID 33623786, 2021).
endometritis (3 papers, 2024 to 2025). An acute or chronic, usually bacterial infectious process affecting the endometrium. "Gene expression levels were considerably higher in endometritis-affected buffaloes than in resistant ones for the genes A2M, TLR2, IRAK3, CCl2, FCAMR, iNOS, ADAMTS20, KCNT2, MAP3K4, MAPK14, FKBP5, and EPHA4." (PMID 38459095, 2024).
fibrosis (3 papers, 2016 to 2021). the formation of excess fibrous connective tissue in an organ or tissue in a reparative or reactive process. "Fibrosis is associated with upregulation of RBL1, CDK9, Renin receptor, mitogen-activated protein kinase p38α (Mapk14 gene)." (PMID 34428743, 2021).
inflammatory bowel disease (3 papers, 2012 to 2023). A spectrum of small and large bowel inflammatory diseases of unknown etiology. "The MAPK14 pathway plays a role in inflammatory bowel disease." (PMID 36925608, 2023).
preeclampsia (3 papers, 2017 to 2023). Preeclampsia is a hypertensive disorder of pregnancy that is characterized by new-onset hypertension with proteinuria presenting after 20 weeks of gestation, and depending on mild or severe forms may initially present with severe headache, visual disturbances, and hyperreflexia. "In contrast, the human placenta from Preeclampsia showed a low level of expression of MAPK14- PPARγ- Syncytin-1 genes." (PMID 34867473, 2021).
Salmonella Infections (3 papers, 2016 to 2021). Infections with bacteria of the genus SALMONELLA. "In the Salmonella infection pathway, MAPK14 is a downstream mediator of the Rho family GTPases CDC42." (PMID 27474500, 2016). "However, only one gene in the Salmonella infection pathway, MAPK14, was predicted to target miR-125b." (PMID 27474500, 2016). "This analysis demonstrated that in the control-fed animals, Salmonella infection led to a transient downregulation of MAPK1, MAPK14, and FASLG at 1 dpi (p < 0.05)." (PMID 29181381, 2017).
tuberculosis (3 papers, 2013 to 2021). A chronic, recurrent infection caused by the bacterium Mycobacterium tuberculosis. "NBXH upregulates Mapk14 expression, regulates the immune response during M. tuberculosis infection, induces BAX translocation and apoptosis, enhances TNF expression, limits M. tuberculosis, and exerts an anti-TB effect." (PMID 34074345, 2021).
amyotrophic lateral sclerosis (2 papers, 2015 to 2023). Amyotrophic lateral sclerosis (ALS) is a neurodegenerative disease characterized by progressive muscular paralysis reflecting degeneration of motor neurons in the primary motor cortex, corticospinal tracts, brainstem and spinal cord. "NF-L binds to Mapk12 (mitogen-activated protein kinase 12), Mapk13, Mapk14, Nefh (neurofilament), Nefm, Prph (peripherin) and Prph2 which are involved in pathway associated to Amyotrophic Lateral Sclerosis (ALS)." (PMID 25561935, 2015).
Anxiety (2 papers, 2022). Intense feelings of nervousness, tension, or panic often arise in response to interpersonal stresses. "Nonetheless, selective deletion of MAPK14 in CD90‐expressing neurons altered anxiety responses and led to activation of JNK, which suggests that p38‐alpha might be involved in nociceptive processing." (PMID 35760453, 2022).
Autoimmunity (2 papers, 2020 to 2021). The occurrence of an immune reaction against the organism's own cells or tissues.
cannabis abuse (2 papers, 2013 to 2018). "The same team recently examined the effect of another cannabinoid-related gene, mitogen-activated protein kinase 14 (MAPK14): they assessed the MAPK14-CNR1 gene–gene interactions in conferring brain volumes abnormalities among subjects with SZ with cannabis abuse." (PMID 24133464, 2013).
chronic kidney disease (2 papers, 2019 to 2025). Impairment of the renal function secondary to chronic kidney damage persisting for three or more months. "This study shows that cell proliferation, differentiation, apoptosis, migration (SRC, HRAS, HSP90AA1, CDK2), and ameliorating chronic kidney disease (MAPK14, F2, LCK, MMP9) appear to play important roles in the therapeutic effect of SQW." (PMID 31275142, 2019).
dilated cardiomyopathy (2 papers, 2014 to 2015). Cardiomyopathy which is characterized by dilation and contractile dysfunction of the left and right ventricles. "In addition to the three structural proteins, the levels of mitogen-activated protein kinase 14 in the left ventricle was higher which is consistent with its reported role in cardiomyocyte survival pathway in response to pressure overload and in the pathogenesis of dilated cardiomyopathy." (PMID 25249829, 2014).
disc degeneration (2 papers, 2016 to 2025). "In addition, factors such as IL-1β, MAPK14, MMP9, and MMP3 can contribute to inflammation and matrix degradation, potentially further interacting with Wnt signaling to exacerbate disc degeneration." (PMID 39623712, 2025).
Granuloma (2 papers, 2022 to 2025). A compact, organized collection of mature mononuclear phagocytes, which may be but is not necessarily accompanied by accessory features such as necrosis. "Among structural cells, the expression of key tissue development genes (MAPK14, GATA6, FOXF1, VEGFA) were markedly elevated in both endothelial and epithelial cell populations derived from MAH granulomas." (PMID 41586350, 2025).
Neonatal sepsis (2 papers, 2018 to 2026). Systemic inflammatory response to infection in newborn babies. "In the TF-DEG regulatory network, MAPK14 was targeted by CEBPB, indicating that CEBPB targeting MAPK14 might function in neonatal sepsis through TNF signaling pathway." (PMID 30497506, 2018). "TSPO, ZAP70, CEBPB targeting MAPK14, has-miR-150 targeting BCL11B might affect the pathogenesis of neonatal sepsis." (PMID 30497506, 2018). "Besides, TSPO, ZAP70, CEBPB targeting MAPK14, has-miR-150 targeting BCL11B might act in the pathogenesis of neonatal sepsis." (PMID 30497506, 2018). "These declared that TSPO, MAPK14, and ZAP70 might play critical roles in neonatal sepsis." (PMID 30497506, 2018).
triple-negative breast carcinoma (2 papers, 2023 to 2024). An invasive breast carcinoma which is negative for expression of estrogen receptor (ER), progesterone receptor (PR), and human epidermal growth factor receptor 2 (HER2). "Interestingly, the in silico binding activity of globospiramine to MAPK14 may also explain its relatively weaker in vitro cytotoxicity against triple-negative breast cancer cell lines, especially MDA-MB-231." (PMID 38727308, 2024).
adrenocortical carcinoma (1 paper, 2020). "Notably, we next validated BMP7 and MAPK14 expression and SMAD1 activation in samples from patients with NSCLC and adrenocortical carcinoma that progressed in the lung after treatment with pembrolizumab and ipilimumab, respectively." (PMID 32973129, 2020).
Alexander disease (1 paper, 2023). Alexander disease (AxD) is a rare neurodegenerative disorder of the astrocytes comprised of two clinical forms: AxD Type I and Type II manifesting with various degrees of macrocephaly, spasticity, ataxia and seizures and leading to psychomotor regression and death. "Likewise, Diseases associated with MAPK14 include Chlamydia and Alexander Disease." (PMID 36641432, 2023).
allergic asthma (1 paper, 2025). A asthma with a basis in a pathological type I hypersensitivity reaction. "Additionally, androgen receptors have been shown to inhibit the inflammatory response in allergic asthma airway epithelial cells through the modulation of MAPK1 and MAPK14." (PMID 40264707, 2025).
ankylosing spondylitis (1 paper, 2024). An autoimmune chronic inflammatory disorder characterized by inflammation in the vertebral joints of the spine and sacroiliac joints. "Among them, AIF1 and IL23R are associated with decreased risk of ankylosing spondylitis; MICA, MAPK14, and ATF6B are linked to increased risk of ankylosing spondylitis." (PMID 38835753, 2024).
autism spectrum disorder (1 paper, 2015). A spectrum of developmental disorders that includes autism, and Asperger syndrome. "These genes include one that has been previously linked to SCZ, Autism Spectrum Disorder and Intellectual Disability (SHANK3) as well as two novel genes that were identified through a protein:protein interaction study (EP300 and MAPK14)." (PMID 26039597, 2015).
bacterial sepsis (1 paper, 2017). "Upregulation of MAPK14 proteins inhibit the expression of iNOS while upregulating the expression of Arginase-1 proteins which are associated with M2 polarization of macrophages during parasitic infection and bacterial sepsis." (PMID 29375545, 2017).
brain tumors (1 paper, 2020). "This study thus highlighted the role of MAPK14 in the anticancer mechanism of action of mebendazole and provides further rationale for the pharmacological targeting of MAPK14 in brain tumors." (PMID 33021050, 2020).